HHLA2 (HHLA2 member of B7 family)
Diseases named in the same sentence as HHLA2 in open-access papers (continued):
Sharing a sentence is not in itself a finding about the gene and the disease.
gastric cancer (continued). "Furthermore, elevated HHLA2 expression was identified as an independent unfavorable prognostic marker for the overall survival of the patients with gastric cancer." (PMID 38786018, 2024). "Therefore, we assessed HHLA2 mRNA levels using qRT-PCR assay in blood specimens obtained from patients with gastric cancer and PBMC specimens obtained from healthy volunteers." (PMID 29774123, 2018). "Accordingly, HHLA2 may exert a costimulatory effect against the T cell-mediated immune response via TMIGD2 in patients with gastric cancer." (PMID 29774123, 2018). "Consequently, we examined HHLA2 expression in blood specimens from patients with gastric cancer, and investigated the relationship between its expression and clinicopathological factors to assess its potential power as a prognostic blood predictor." (PMID 29774123, 2018). "Based on the median value of the relative HHLA2 mRNA copies, 111 patients with gastric cancer were divided into a high-expression group (n = 55) and a low-expression group (n = 56) to investigate the relationship between expression of HHLA2 and clinicopathological factors." (PMID 29774123, 2018). "Although the immunological role of the HHLA2 signaling pathway remains unclear, a new technique that allows gastric tumor cells to express HHLA2 may enable a targeted immunotherapy that controls its signaling pathway in patients with unresectable advanced gastric cancer." (PMID 29774123, 2018). "Therefore, the HHLA2 molecule may be a potential biomarker for predicting malignant behavior in patients with gastric cancer." (PMID 29774123, 2018). "Supposing the assessment of HHLA2 expression in the primary tumor site is a tool for predicting tumor response against HHLA2-targeted immunotherapy, a blood biopsy to determine HHLA2 expression could be utilized to monitor sequential therapeutic effects in patients with advanced gastric cancer." (PMID 29774123, 2018). "Thus, HHLA2 may be a promising blood marker for predicting prognosis after treatment in patients with gastric cancer." (PMID 29774123, 2018). "In gastric cancer, elevated TMIGD2 expression predicts a bad prognosis, mainly when its ligand HHLA2 is strongly co-expressed." (PMID 37261362, 2023). "Contrary to these results, patients with negative HHLA2/TMIGD2 expression presented a significantly higher 5-year OS compared to the positive groups of gastric cancer." (PMID 37261362, 2023). "Of the four gastric cancer cell lines, only MKN-45 showed expression of HHLA2 mRNA." (PMID 29774123, 2018). "However, there have been no studies assessing the clinical significance of HHLA2 expression in blood specimens and tumor tissues obtained from patients with gastric cancer." (PMID 29774123, 2018). "Furthermore, we confirmed the absence of HHLA2 expression in the majority of gastric cancer cell lines that were examined." (PMID 29774123, 2018).
osteosarcoma (16 papers, 2016 to 2024). A usually aggressive malignant bone-forming mesenchymal neoplasm, predominantly affecting adolescents and young adults. "In osteosarcoma, HHLA2 is upregulated in metastasis tumor samples and associated with worse clinical outcomes." (PMID 38225273, 2024). "While HHLA2 expression is associated with worse survival in patients with osteosarcoma, its expression and significance of HHLA2 is ill defined in other types of solid tumors." (PMID 32509772, 2020). "HHLA2 expression has been associated with metastatic properties of osteosarcoma cells and poor survival of osteosarcoma patients." (PMID 31370265, 2019). "Osteosarcoma cells express HERV-H LTR-associating 2 (HHLA2), PDL-1 and B7-H3, three members of the B7 proteins that contribute to local immunosuppression." (PMID 31370265, 2019). "In patients with osteosarcoma, high HHLA2 expression was associated with a significantly worse prognosis." (PMID 29774123, 2018). "Overall, we have shown that HHLA2 is expressed in the majority of osteosarcoma tumors and its expression is associated with metastatic disease and poorer survival." (PMID 27531281, 2016). "Also, HHLA2 expression in osteosarcoma was reported to be associated with metastases." (PMID 34181347, 2021). "For example, a high HHLA2 expression level indicates a poor prognosis in osteosarcoma, colorectal cancer, and triple-negative breast cancer." (PMID 33962626, 2021). "In TNBC and osteosarcoma, the high expression rates of HHLA2 were 56% (28/50) and 68% (42/62), respectively." (PMID 30885276, 2019). "Our results, demonstrating the high frequency of HHLA2 protein expression, mirror the prevalence of PD-L1 mRNA expression in osteosarcoma." (PMID 27531281, 2016). "Here we present the first study on the expression and clinical significance of HHLA2, a member of the B7 family of immune checkpoint molecules, in osteosarcoma." (PMID 27531281, 2016). "Our results demonstrate that HHLA2 expression in osteosarcoma is on the higher end of the spectrum, similar to the frequency seen in breast cancer." (PMID 27531281, 2016). "HHLA2 expression was validated in a second set of osteosarcoma tumors, mostly collected at the time of definitive surgery." (PMID 27531281, 2016). "In this study, we assess the expression patterns of HHLA2 in osteosarcoma in the context of the immune microenvironment." (PMID 27531281, 2016). "HHLA2 protein expression was evaluated in primary tumor specimens and metastatic disease using an osteosarcoma tumor microarray (TMA) (n = 62)." (PMID 27531281, 2016). "Due to the high levels of TIL infiltration in many osteosarcoma tumors, we assessed if HHLA2 was expressed on tumor cells or on immune cells by performing double IF of HHLA2 and CD45, a myeloid cell marker." (PMID 27531281, 2016). "Due to the prevalence of HHLA2 expression in osteosarcoma, this pathway needs to be further explored in patients who do not respond to conventional therapies." (PMID 27531281, 2016). "We sought to evaluate the prevalence and clinical significance of the newest immune checkpoint, HHLA2, in osteosarcoma." (PMID 27531281, 2016). "Osteosarcoma cells express several subtypes from the B7 family including HHLA2 and PDL-1 proteins." (PMID 37424864, 2023). "In addition, HHLA2 was more prevalent than PD‐L1 in intrahepatic cholangiocarcinoma and osteosarcoma." (PMID 34152094, 2021). "Previous studies reported that HHLA2 was widely expressed in patients with PD‐L1‐negative NSCLC, intrahepatic cholangiocarcinoma, and osteosarcoma, suggesting that HHLA2 might be a promising immunotherapy target." (PMID 34152094, 2021). "HHLA2 (B7H7/B7-H5/B7y), a newly defined B7 family member, is a co-inhibitory molecule expressed in multiple cancers, including lung, breast and pancreatic cancers as well as melanoma, and osteosarcoma and shows limited expression in normal tissues." (PMID 32509772, 2020).
osteosarcoma (continued). "Taken together, these observations suggest that the HHLA2 pathway may represent a more important immunosuppressive mechanism in the human osteosarcoma tumor microenvironment." (PMID 27531281, 2016). "Along with previously reported findings that HHLA2 is a T cell co-inhibitor, these results suggest that HHLA2 may be a novel immunosuppressive mechanism within the osteosarcoma tumor microenvironment." (PMID 27531281, 2016). "We found that HHLA2 is expressed in the majority of osteosarcoma samples." (PMID 27531281, 2016). "Furthermore, targeting HHLA2 in addition to other immune checkpoint inhibitors may be required to completely inhibit the pathway and sensitize osteosarcoma to immune mediated clearance." (PMID 27531281, 2016). "The expression pattern and clinical relevance of HHLA2 have so far been studied in detail in triple negative breast cancer (TNBC), osteosarcoma and non-small-cell lung cancer (NSCLC)." (PMID 30885276, 2019). "The poor prognostic value of HHLA2 was also reported in clear cell RCC, osteosarcoma and TNBC." (PMID 34181347, 2021). "The majority of HHLA2 expression was independent of CD45, suggesting HHLA2 is most frequently expressed on non-myeloid cells, most likely on osteosarcoma cells." (PMID 27531281, 2016). "A previous study examined the expression of HHLA2 in a variety of cancers, not including osteosarcoma, and demonstrated variable expression in different histologic subgroups ranging from zero to 70%24." (PMID 27531281, 2016). "To date, HHLA2 expression in osteosarcoma has not been examined." (PMID 27531281, 2016). "Combining our result and previous studies, we hypothesized that, for osteosarcoma patients without response to anti-PD1/PDL1 therapy, targeting VTCN1 or HHLA2 was a potentially promising treatment method." (PMID 38225273, 2024).
colorectal cancer (13 papers, 2019 to 2025). A primary or metastatic malignant neoplasm that affects the colon or rectum. "A more recent study aimed to investigate the HERV-H LTR-association protein 2 (HHLA2) in colorectal cancer and its association with clinicopathological features." (PMID 38655281, 2024). "Our recent work studied associations between HHLA2 and microsatellite instability in colorectal cancer." (PMID 38786018, 2024). "Moreover, GSEA showed that HHLA2 was linked to critical hallmark pathways in colorectal cancer related to cell cycle regulation and apoptosis." (PMID 36982953, 2023). "Given that HHLA2 undergoes glycosylation by the STT3 oligosaccharyltransferase complex in colorectal cancer, and that STT3A was identified as an HHLA2-interacting protein in our study, we investigated the role of HHLA2 glycosylation in c-Met binding." (PMID 40394703, 2025). "There are reports showing correlations between higher HHLA2 expression and more advanced T and N stages, as well as more prominent distant recurrence in colorectal cancer and a more advanced TNM stage." (PMID 38786018, 2024). "We plan to extend our previous study on HHLA2 expression in colorectal cancer of the European population with a 5-year follow-up." (PMID 38731979, 2024). "Further studies must elucidate the mechanisms of HHLA2 overexpression and its therapeutic values in colorectal cancer." (PMID 36982953, 2023). "Taken together, the GSEA and GO data suggest that HHLA2 participates in various signaling pathways related to the progression of colorectal cancer." (PMID 36982953, 2023). "We reveal the role of HHLA2 expression as well as a stimulatory and inhibitory immune checkpoint in colorectal cancer." (PMID 36982953, 2023). "We further performed a comprehensive analysis by the web-based tool Camoip and investigated the immune composition of colorectal cancer in relation to HHLA2 expression." (PMID 36982953, 2023). "Analysis of the immune infiltration landscape of HHLA2 in colorectal cancer was made by the web-based tool Camoip." (PMID 36982953, 2023). "In 2020, Wang and colleagues retrieved and analyzed the TCGA database and reviewed three B7 family molecules, including B7-H3, VISTA and HHLA2, as the most expressed in patients with colorectal cancer." (PMID 35682714, 2022). "Because of the limited number of studies and contradictory results, it is uncertain whether HHLA2 can be considered a potential prognostic marker for colorectal cancer." (PMID 38786018, 2024). "In colorectal cancer, tissues exhibit HHLA2 expression in the majority of cases." (PMID 38786018, 2024). "Furthermore, the immune infiltration landscape and HHLA2-related pathways in colorectal cancer using available online datasets were analyzed." (PMID 36982953, 2023). "Additionally, we analyzed HHLA2-related pathways in colorectal cancer using available online datasets." (PMID 36982953, 2023). "Upregulation of HHLA2 was also demonstrated in other studies considering colorectal cancer." (PMID 36982953, 2023). "The exact function of HHLA2 in colorectal cancer is still not fully understood." (PMID 36982953, 2023). "In a colorectal cancer study, HHLA2 expression in cancer tissues was higher than in adjacent tissues, and the expression level was significantly associated with the depth of invasion and CD8 + T cell infiltration status and could predict high mortality rates." (PMID 32536823, 2020). "The importance of HHLA2 in tumor genesis and invasion in colorectal cancer remains unclear." (PMID 36982953, 2023). "However, the value of HHLA2 in colorectal cancer remains unknown and needs further investigation." (PMID 36982953, 2023).
pancreatic cancer (13 papers, 2018 to 2025). "Seven studies on pancreatic cancer indicated varied HHLA2 expression patterns, with high expression levels associated with better prognosis and improved overall survival." (PMID 40255615, 2025). "As opposed to other molecules in the B7 family that regulate the processes of pancreatic cancer, the current study found that overexpression of the HHLA2 molecule seems to be associated with a good prognosis." (PMID 36499340, 2022). "Intratumoural HHLA2 expression was also positively associated with survival and recurrence in pancreatic cancer patients alone, while in ampullary cancer patients a similar trend was observed, but the differences were not statistically significant." (PMID 32071413, 2020). "The association of HHLA2 expression with cancer-specific survival and recurrence was statistically significant for the pancreatic cancer subgroup while a similar trend was found for the ampullary cancer subgroup." (PMID 32071413, 2020). "Because the pancreato-biliary subtype of ampullary cancer and pancreas cancer are closely related cancer types, we first analysed HHLA2 expression in the combined cohort." (PMID 32071413, 2020). "Analysis of associations of HHLA-2 expression with clinicopathologic characteristics showed that HHLA2 was more frequently expressed in ampullary tumours compared to pancreatic tumours (93% vs 67%)." (PMID 32071413, 2020). "In 77.17% of PDAC cases, the expression of HHLA2 is strongly associated with an improved post-surgical prognosis, indicating functions of HHLA2 as a costimulatory ligand in pancreatic cancer, activating CD8+ T cell proliferation and improving patient prognosis." (PMID 39911323, 2025). "Both Yan and Patrick demonstrated that the augmentation of intratumoral HHLA2 expression in patients with pancreatic cancer after tumor resection led to an increased survival rate." (PMID 36499340, 2022). "This review summarizes the expression of PD-1, PD-L2, B7-H3, B7-H4, VISTA, and HHLA2 in the immune microenvironment of pancreatic cancer and their roles in promoting tumor metastasis and invasion." (PMID 36499340, 2022). "Further studies on HHLA2 can help to elucidate the complex tumor immune microenvironment and provide strategies for immunotherapy of pancreatic cancer." (PMID 36499340, 2022). "In conclusion, HHLA2 is widely expressed in tumour cells of pancreatic cancer and ampullary cancers." (PMID 32071413, 2020). "The aim was to determine the expression, prevalence and biological relevance of HHLA2 protein expression in two closely related human cancer types, namely pancreatic cancer and ampullary cancer." (PMID 32071413, 2020). "HHLA2 expression levels were retrospectively determined by immunohistochemistry in tissue micro-arrays of surgically resected tumours of 122 pancreatic cancer patients and 72 patients with ampullary cancer of the pancreato-biliary subtype." (PMID 32071413, 2020). "Consistent with previous reports on HHLA2 expression in several types of cancer, including pancreatic cancer, we observed both membranous and cytoplasmic expression in cancer cells." (PMID 32071413, 2020). "HHLA2 was expressed at variable levels by tumour cells in 67% of pancreatic tumours and 93% of ampullary tumours." (PMID 32071413, 2020). "In our study, we found that silencing of HHLA2 can inhibit the EMT process of pancreatic cancer cells, and the mechanism may be related to the regulation of EGFR/MAPK /mTOR/AKT/ERK1/2 signaling pathway." (PMID 38762741, 2024). "HHLA2 in cancer cells may stimulate immune response in pancreatic cancer, which is a sign of a good prognosis but plays the opposite role in immune cells." (PMID 38786018, 2024). "Similarly, we have previously reported that cancer cell expression of the co-inhibitory immune checkpoint molecules PDL-1 and HHLA-2 is more prevalent in ampullary cancer patients than in pancreatic cancer patients (p=0.043)." (PMID 33996541, 2021).
pancreatic cancer (continued). "Moreover, 53% of ampullary tumours expressed high levels of HHLA2 compared to 13% of pancreatic tumours." (PMID 32071413, 2020). "However, the exact functions of HHLA2 in pancreatic cancer (PC) remain incompletely elucidated." (PMID 38762741, 2024). "Moreover, patients positive for HHLA2 exhibited delayed cancer recurrence in pancreatic cancer." (PMID 38786018, 2024). "However, recent research indicates that HHLA2 may function as a co-stimulatory ligand in pancreatic cancer." (PMID 36499340, 2022). "While pancreatic cancer and ampullary cancer of the pancreato-biliary subtype are histologically indistinguishable and show many similarities at the molecular level, we found that HHLA2 was more frequently expressed in ampullary tumours compared to pancreatic tumours." (PMID 32071413, 2020). "Moreover, they also observed HHLA-2 expression in precancerous pancreas lesions present in tumour-surrounding tissues, suggesting that induction of HHLA2 in pancreatic cancer cells may already occur early during oncogenesis." (PMID 32071413, 2020). "As a consequence of the absence of HHLA2 expression in laboratory mice, the involvement of HHLA2 in pancreatic cancer has not yet been investigated thoroughly." (PMID 36499340, 2022). "Several studies have reported that HHLA2 is a negative indicator in colon, lung and pancreatic cancers." (PMID 32509772, 2020). "Interestingly, Yan et al26 reported HHLA2 expression in inflamed ducts in peritumoural tissues in 10% of pancreatic cancer patients, while normal duct epithelial cells do not express HHLA-2, suggesting that inflammation can induce HHLA-2 expression on pancreatic ductal epithelial cells." (PMID 32071413, 2020).
breast carcinoma (12 papers, 2016 to 2024). "Our finding was not consistent with previous report that elevated expression of HHLA2 may be associated with abnormal copy-number variant of HHLA2 DNA in basal breast cancer." (PMID 31379814, 2019). "The previous studies showed that copy number variant of HHLA2 DNA may be involved in the dysregulation of HHLA2 expression level in breast cancer." (PMID 31379814, 2019). "However, patients with high expression of HHLA2 have a higher risk of lymph node metastasis and advanced breast cancer." (PMID 29774123, 2018). "It has been shown that immune-related pathways take part in the process of ferroptosis and HHLA2, which was found to be differently expressed in breast cancer and could be involved in ferroptosis during the disease." (PMID 38786018, 2024). "It is unclear whether HHLA2 has prognostic or therapeutic value in breast cancer." (PMID 38786018, 2024). "There are not many reports tackling the issue of HHLA2 expression in breast cancer." (PMID 38786018, 2024).